STK35 (serine/threonine kinase 35)
Synonyms: CLIK1; STK35L1; bA550O8.2
Tractability: Small molecule: a high-quality ligand is known; it belongs to a druggable protein family. PROTAC: it is named in the literature on targeted protein degradation; ubiquitination databases record sites on it; a small molecule that binds it is known.
Target class: Kinase; Enzyme; Other protein kinase NKF4 family; Other protein kinase group; Protein Kinase
Safety:
Unwanted effects reported when the protein is acted on. In parentheses: how it was acted on, where the effect was seen, and who reports it.
arterial thrombosis (inhibition; cardiovascular; source: Brennan et al. (2024))
Hypertension (inhibition; cardiovascular; source: Brennan et al. (2024))
QT prolongation (inhibition; cardiovascular; source: Brennan et al. (2024))
cardiac arrhythmia (cardiovascular system; source: Lamore et al. (2017))
Gene: Protein-coding gene on chromosome 20 (2,101,767 to 2,177,038, forward strand). Ensembl gene ENSG00000125834.
Subcellular location: Nucleus; Nucleus, nucleolus; Cytoplasm
Subcellular location (Human Protein Atlas): Nuclear bodies; Nucleoplasm
Gene Ontology:
Molecular function: protein binding; ATP binding; protein kinase activity; protein serine kinase activity; protein serine/threonine kinase activity
Biological process: negative regulation of G2/M transition of mitotic cell cycle; negative regulation of G2/MI transition of meiotic cell cycle
Cellular component: nucleoplasm; cytoplasm; nucleus; nucleolus
Genetic constraint (gnomAD): Loss-of-function variants: 17 observed, 33.2 expected, observed/expected ratio (o/e) 0.51, 90% interval 0.35 to 0.77. The synonymous counts are far from expectation, so gnomAD's model fits this gene poorly and the ratio says little. Missense variants: 594 observed, 669.92 expected, observed/expected ratio (o/e) 0.89, 90% interval 0.83 to 0.95. Synonymous variants: 385 observed, 284.82 expected, observed/expected ratio (o/e) 1.35, 90% interval 1.24 to 1.47.
Homologues: Orthologues: chimpanzee STK35 (99% identical), macaque STK35 (98% identical), pig STK35 (93% identical), rabbit STK35 (93% identical), guinea pig STK35 (92% identical), mouse Stk35 (88% identical), rat Stk35 (87% identical), tropical clawed frog stk35l (59% identical), zebrafish stk35 (55% identical), zebrafish stk35l (52% identical). Paralogues in human: PDIK1L (43% identical), WEE1 (20% identical), WEE2 (18% identical), PKMYT1 (17% identical), EIF2AK3 (17% identical), EIF2AK4 (16% identical), EIF2AK2 (14% identical), EIF2AK1 (14% identical).
Diseases named in the same sentence as STK35 in open-access papers:
STK35 is named in the same sentence as 16 diseases in open-access papers, as found by Europe PMC text mining. Sharing a sentence is not in itself a finding about the gene and the disease. The quoted sentences say what the papers report.
colorectal cancer (8 papers, 2009 to 2025). A primary or metastatic malignant neoplasm that affects the colon or rectum. "STK35 can influence the chemoresistance of colorectal cancer by promoting glycolysis and inhibiting apoptosis through the regulation of the AKT pathway." (PMID 38584840, 2024). "One report showed that NEDD4L regulated the AKT signaling pathway by ubiquitinating STK35, ultimately affecting chemoresistance in colorectal cancer." (PMID 38027016, 2023). "NEDD4L can downregulate STK35 via ubiquitination, resulting in apoptosis in colorectal cancer cells." (PMID 38027016, 2023). "Correlation between the STK35 protein expression and clinicopathological parameters in patients with colorectal cancer." (PMID 33117809, 2020). "Various high throughput studies indicate that STK35 could be involved in various human diseases such as colorectal cancer and malaria." (PMID 19756140, 2009). "The STK35 gene was found upregulated specifically in colorectum cancer." (PMID 19756140, 2009). "Additionally, STK35 inhibits apoptosis and influences chemoresistance in colorectal cancer." (PMID 34722508, 2021). "STK35 is ubiquitinated by NEDD4L and promotes glycolysis by regulating the AKT signaling pathway to affect colorectal cancer chemotherapy resistance." (PMID 38027016, 2023). "For example, NEDD4L can degrade serine/threonine kinase 35 (STK35) by ubiquitination and subsequently inhibit glycolysis and induce apoptosis of colorectal cancer cells via inhibiting the Akt signaling pathway." (PMID 37580757, 2023).
osteosarcoma (4 papers, 2009 to 2024). A usually aggressive malignant bone-forming mesenchymal neoplasm, predominantly affecting adolescents and young adults. "STK35 has also been named as Clik1 (CLP36 Interacting Kinase 1) based on one study that showed an association of STK35 with CLP36 after overexpression of both proteins in osteosarcoma cells." (PMID 19756140, 2009). "STK35 regulates apoptosis and proliferation in osteosarcoma cells in osteosarcoma, exhibiting oncogenic properties." (PMID 39185313, 2024). "It has been reported that the downregulation of STK35 promotes apoptosis and decreases proliferation by activating caspase 3 and caspase 7 in osteosarcoma cells." (PMID 34722508, 2021). "Previously, it has been shown that myc-tagged Clik1 (STK35) translocated from the nucleus to actin stress fibers upon coexpression with EGFP-CLP36 in U2OS osteosarcoma cells." (PMID 19756140, 2009). "Additionally, it was observed that STK35 modulates apoptosis and proliferation in osteosarcoma." (PMID 38584840, 2024).
acute myeloid leukemia (1 paper, 2024). Acute myeloid leukemia (AML) is a group of neoplasms arising from precursor cells committed to the myeloid cell-line differentiation. "In acute myeloid leukemia (AML), CTDSPL2 dephosphorylates the kinases STK35 and PDIK1L, supporting the proliferation of AML cancer cells and affecting the expression of genes involved in amino acid biosynthesis and transport." (PMID 39209829, 2024).
gastric cancer (1 paper, 2024). A primary or metastatic malignant neoplasm involving the stomach. "STK35 has been linked to immune signatures in gastric cancer, suggesting it may impact the immune response and effectiveness of immunotherapy." (PMID 39185313, 2024).
keratoconus (1 paper, 2021). A degenerative, structural disorder of the eye, characterized by a cone-shaped protrusion of the cornea. "Expression of STK35, that is associated in our analyses (rs6106210, p = 2.85 × 10−11), was increased two-fold in keratoconus corneas (FDR = 3.24 × 10−03) and RAB11FIP4 (rs56161228, p = 2.70 × 10−10) found in our study, was increased by 2.4 fold (FDR = 3.24 × 10−03)." (PMID 33649486, 2021).
Parkinson disease (1 paper, 2020). A progressive degenerative disorder of the central nervous system characterized by loss of dopamine producing neurons in the substantia nigra and the presence of Lewy bodies in the substantia nigra and locus coeruleus. "It has also been reported that STK35 is associated with programmed cell death, and STK35 gene expression is altered in Parkinson disease." (PMID 33117809, 2020).
prion disease (1 paper, 2022). A transmissible disease that is caused by a protein that is able to induce abnormal folding of normal cellular proteins, leading to characteristic spongiform brain changes, which are associated with neuronal loss without an inflammatory response. "SPRN encodes the shadow of prion protein, associated with neurodegenerative human prion diseases including Creutzfeldt–Jakob disease, while knockdown of STK35 in endothelial cells alleviates their migratory ability." (PMID 35328807, 2022).
Stroke (1 paper, 2022). Sudden impairment of blood flow to a part of the brain due to occlusion or rupture of an artery to the brain. "Moreover, CBX7 (target of miR-4446), SPRN and STK35 (targets of miR-6721-5p) have also been studied in stroke models." (PMID 35328807, 2022).
cancer (5 papers, 2015 to 2023). A tumor composed of atypical neoplastic, often pleomorphic cells that invade other tissues. "Although the detailed biological functions of STK35 are still being investigated, STK35 has regulatory roles in cell-cycle modulation, and its abnormal cellular levels are implicated in various human diseases including cancer." (PMID 33117809, 2020). "Serine/threonine kinase 35 (STK35) regulates the cell cycle and is frequently associated with cancer progression, whereas little is known about its specific roles in CRC." (PMID 33117809, 2020). "Thus, the directional effects of the risk alleles on expression of STK35 or PDLIM5 are consistent with increased cancer risk." (PMID 27704213, 2017). "The AKT pathway is also involved in modulating chemoresistance of human cancer cells, which, together with the findings on STK35-CRC resistance toward 5-FU, indicates close relationships among STK35, the AKT signaling pathway, and CRC chemoresistance." (PMID 33117809, 2020). "Gene set enrichment analysis demonstrated that the expression of STK35 was significantly (P < 0.001) correlated with cancer cell apoptosis, glycolysis, and AKT pathways." (PMID 33117809, 2020). "The expression of human STKs have been reported to be frequently modulated in a variety of human cancers, and particularly, the STK35 gene is noticeably altered in human CRC." (PMID 33117809, 2020). "Thus, we proposed that NEDD4L can inhibit Akt activation in ccRCC possibly through degrading its upstream activators such as STK35, SphK2, CTR1, and PIK3CA, which were previously reported in different cancers." (PMID 37580757, 2023).
tumor (2 papers, 2017 to 2020). "We also demonstrate that STK35 promotes both in vitro cellular activities and in vivo tumor growth of CRC, potentially through regulating the AKT signaling pathway." (PMID 33117809, 2020). "We demonstrate that STK35 is highly expressed in CRC tumor tissues and that its expression is positively correlated with the mortality rate of CRC patients." (PMID 33117809, 2020). "According to the datasets from TCGA and the GSE9348, the mRNA expression levels of STK35 in tumor tissues of CRC patients were noticeably (P < 0.001 and <0.01, respectively) higher than those in normal tissues." (PMID 33117809, 2020). "In the current study, we proposed to explore the correlation between STK35 and prognostic conditions in CRC patients, the roles of STK35 in CRC cellular activities and tumor development, and the possible mechanisms underlying the functions of STK35." (PMID 33117809, 2020). "Relying on the analyses of patient data collected from both online databases and those of our hospital, we detected a notably higher expression of STK35 in the tumor tissues from CRC patients at both the protein and mRNA levels." (PMID 33117809, 2020). "The effect of STK35 on tumor growth was evaluated by subcutaneously injecting nude mice with STK35 knockdown-SW620 cells." (PMID 33117809, 2020). "Similarly, STK35 knockdown notably (P < 0.001) reduced the tumor weight at day 33 in relation to the control group." (PMID 33117809, 2020). "Moreover, multivariate analysis revealed that STK35 protein expression was noticeably associated with two clinicopathological parameters in the CRC patients, including tumor size (P = 0.016) and T classification (P = 0.024)." (PMID 33117809, 2020). "Similarly, based on Q-PCR, we also found that the transcriptional level of STK35 in the 131 tumor tissues from CRC patients in our hospital was significantly (P < 0.001) higher than that in the 30 normal tissues." (PMID 33117809, 2020). "In the current study, the knockdown of STK35 in CRC cells elevated their apoptotic rate and reduced their proliferation, tumor growth, and energy metabolism, including both mitochondrial respiration and glycolytic flux." (PMID 33117809, 2020). "In the current study, we observed the anti-CRC functions of 5-FU in a dose-dependent manner as expected, whereas the overexpression of STK35 in CRC cells partially reversed these effects, such as the promotion of apoptosis, tumor growth inhibition, and survival improvement in an in vivo mouse model." (PMID 33117809, 2020). "In addition, we demonstrate that STK35 promotes CRC cellular viability, energy metabolism, tumor growth, and chemoresistance." (PMID 33117809, 2020). "Through bioinformatics analysis, the survival probability in patients following CRC diagnosis and treatments was found to be negatively correlated with the protein expression levels of STK35, demonstrating that STK35 could be an indicator of CRC tumor recurrence." (PMID 33117809, 2020).
STK35 also shares sentences with these, for which no sentence is quoted: malaria (2 papers); cardiomyopathy (1); diabetes (1); endothelial dysfunction (1); glioma (1); scoliosis (1).